ZEB1 (zinc finger E-box binding homeobox 1)
Diseases named in the same sentence as ZEB1 in open-access papers (continued):
Sharing a sentence is not in itself a finding about the gene and the disease.
pulmonary fibrosis (continued). "The mTOR and ZEB1 expression in pulmonary fibrosis patients significantly correlated with the fibrosis score and lung function decline, indicating that it may be related to the prognosis of pulmonary fibrosis." (PMID 25358403, 2014). "Three proteins (mammalian target of rapamycin, mTOR; zinc finger E-box-binding homeobox 1, ZEB1; Rho-associated, coiled-coil containing protein kinase 1, ROCK1) may be related to pulmonary fibrosis." (PMID 25358403, 2014). "Because our patients included some patients with CTD-ILD, further studies involving large numbers of homogeneous IPF patients are warranted to determine whether mTOR and ZEB1 are true prognostic markers of pulmonary fibrosis." (PMID 25358403, 2014). "Thus, our study first suggests that the HIF-1α-ZEB1-EMT pathway is involved in pulmonary fibrosis." (PMID 26819949, 2015). "Thus, mTOR and ZEB1 expression may be related with the prognosis of pulmonary fibrosis and disease progression." (PMID 25358403, 2014). "Nevertheless, it was demonstrated that VitD deficiency contributed to increasing expression of TGF-β1 and ZEB1, which in turn, mediated EMT in bleomycin-induced pulmonary fibrosis." (PMID 37391399, 2023). "Susceptibility to CS-induced pulmonary fibrosis might be influenced by genetic variations in EMT-related genes, such as Snail Family Transcriptional Repressor 1 (SNAI1), Twist Family BHLH Transcription Factor 1 (TWIST1), and Zinc Finger E-Box Binding Homeobox 1 (ZEB1)." (PMID 37371940, 2023). "Besides, in ALI model mice, intratracheal administration of ZPM@PDE-siZEB1/2 could simultaneously deliver siZEB1 and siZEB2 into the inflammatory lung and effectively silence ZEB1/2, thereby delaying the progression of LPS-induced early pulmonary fibrosis in ALI mice." (PMID 35923570, 2022). "Zinc finger E-box binding homeobox 1 and 2 (ZEB1/2) are highly expressed in the early stage of ALI and are positively correlated with the progression of pulmonary fibrosis." (PMID 35923570, 2022). "Our study observed elevation of HIF-1α and ZEB1 protein levels in both the fibrotic lung tissues in vivo and hypoxic pneumocytes in vitro, which correlated with EMT activation and lung fibrosis." (PMID 26819949, 2015). "We first demonstrated that mTOR, ZEB1 and ROCK1 was expressed in hyperplastic alveolar epithelial cells of human pulmonary fibrosis lungs." (PMID 25358403, 2014). "This study was performed to identify the clinical significance of mTOR, ZEB1, and ROCK1 expression in the lung tissues of idiopathic pulmonary fibrosis and UIP pattern connective tissue disease related interstitial lung disease (CTD-ILD) patients." (PMID 25358403, 2014). "This was the first study to evaluate mTOR, ZEB1, and ROCK1 expression in the lung tissues of pulmonary fibrosis patients." (PMID 25358403, 2014). "We assessed the clinical significance of mTOR, ZEB1, and ROCK1 expression in human pulmonary fibrosis of usual interstitial pneumonia (UIP) pattern." (PMID 25358403, 2014). "The expression of mTOR, ZEB1, and ROCK1 was increased in most of the lung tissues of pulmonary fibrosis patients." (PMID 25358403, 2014). "Additionally, ionizing radiation markedly elevates the RNA-binding protein MSI2 in AT2 cells, triggering ZEB1-driven EMT, collagen deposition and radiation-induced pulmonary fibrosis." (PMID 40988754, 2025). "Such interplay between ZEB1 and STAT3 may contribute to the pathogenesis of pulmonary fibrosis induced by COVID-1967,72." (PMID 40593827, 2025). "Interestingly, we also have identified significant DEG-enrichments of target gene sets for five TFs, TCF12, ZEB1, NR3C1, TEAD4 and JUN, which were previously reported to be the regulators in idiopathic pulmonary fibrosis." (PMID 39103936, 2024).
pulmonary fibrosis (continued). "In lungs, ZEB1 antisense RNA 1 (ZEB1-AS1) lncRNA acting as miR-141-3p sponge downregulates miR-141-3p levels, which increases the expression of miR-141-3p target ZEB1 in lung tissues of IPF and in TGF-ß1-stimulated alveolar type II epithelial cells, which promotes pulmonary fibrosis." (PMID 37511619, 2023). "Finally, the released siZEB1/2 can inhibit the expression of ZEB1/2, leading to EMT attenuation and alleviating early pulmonary fibrosis in LPS-induced ALI mice." (PMID 35923570, 2022). "Therefore, it is hypothesized that mTOR pathway, ZEB1, and ROCK1 may play a role in the pathogenesis of pulmonary fibrosis." (PMID 25358403, 2014). "However, whether the hypoxia-HIF-1α-ZEB1-EMT pathway is involved in pulmonary fibrosis has not been reported." (PMID 26819949, 2015).
endometriosis (18 papers, 2015 to 2025). The growth of functional endometrial tissue in anatomic sites outside the uterine body. "ZEB1 protein is expressed at high levels in the epithelial cells of endometriotic tissue, while it is not expressed in normal endometrium, which makes the epithelial expression of ZEB1 a hallmark of endometriosis." (PMID 37685721, 2023). "Unfortunately, in the results of our study, we did not observe any association between plasma or peritoneal fluid zinc finger E-box-binding homeobox 1 and 2 levels and the incidence of endometriosis." (PMID 36289723, 2022). "ZEB1 protein is expressed at high levels in the epithelial cells of endometriotic tissue, while it is not expressed in the normal endometrium, which makes the epithelial expression of ZEB1 a hallmark of endometriosis." (PMID 37685721, 2023). "Combining these findings, we may infer that implantation of an ectopic endometrial cell in women with deep infiltrative endometriosis in the ovary is linked with lower ZEB1 expression and higher miR-200b expression when compared to the matched eutopic endometrium." (PMID 40002936, 2025). "In another study, miRNA 200b was reported to play a role in the pathogenesis of endometriosis by regulating the stem cell phenotype, proliferation, and invasive extension formation in endometriotic cells by targeting ZEB1, ZEB2, and KLF4." (PMID 40572723, 2025). "In a previous article, we investigated the expression profile of ZEB1 in different forms of endometriosis, finding different expression levels between eutopic endometrium and endometriotic lesions." (PMID 40002936, 2025). "The eutopic endometrium of deep infiltrative endometriosis is characterized by a state of ZEB1 and miR-200b over-expression while at ovarian endometriosis there is a state of under-expression of these genes in the eutopic endometrium." (PMID 40002936, 2025). "In the eutopic endometrium of women with endometriosis, there is a balanced expression of mesenchymal genes (ZEB1) and their suppressors (miR-200b), which maintains the epithelial phenotype of the cells." (PMID 40002936, 2025). "When we analyzed the expression profiles of these genes across the two endometriosis groups, we discovered that the eutopic endometrium of deep infiltrative endometriosis exhibits considerable overexpression of ZEB1 (p = 0.014) and miR-200b (p = 0.045)." (PMID 40002936, 2025). "ZEB1 expression was reduced in cysts from the deep infiltrative endometriosis group, but raised in simple ovarian endometriotic cysts when compared to their associated eutopic endometrium." (PMID 40002936, 2025). "The aim of this study was to compare levels of ZEB1 and ZEB2 in the peritoneal fluid and plasma between patients with and without endometriosis in order to assess their utility in the endometriosis diagnostic process." (PMID 36289723, 2022). "MALAT1 was identified as a sponge of miR-200c involved in the regulation of endometriosis stoma cell proliferation and migration by promoting ZEB1 and ZEB2 expression in women with the disease." (PMID 34768856, 2021). "In vitro gene targeting assays in primary human endometriotic stroma cells (ESCs) indicated that this lncRNA regulates epithelial–mesenchymal transition (EMT) in endometriosis by regulating transcription of the EMT-related transcription factor ZEB1." (PMID 34768856, 2021). "Several transcription factors known to play critical roles in EMT, such as Snail, Twist and ZEB1, are also reported to be upregulated in endometriosis." (PMID 27062244, 2016). "However, we discovered that ZEB1 and miR-200b expression were differentially regulated between the two endometriosis subgroups, ranging from eutopic endometrium to endometriotic cysts." (PMID 40002936, 2025). "There is also an example of higher ZEB1 expression in tissues altered by endometriosis." (PMID 36289723, 2022).
endometriosis (continued). "More recently, PI3K/AKT/mTOR signaling pathway targeted by the miR-199a-5p/ZEB1 axis could inhibit the epithelial-mesenchymal transition of ovarian ectopic endometrial stromal cells during endometriosis." (PMID 34055578, 2021). "Overexpression of miR-33b via inhibiting ZEB1/Wnt/β-catenin signaling pathway could promote endometriosis." (PMID 32850438, 2020). "miR-200c by targeting MALAT1/ZEB1/ZEB2 could suppress endometriosis." (PMID 32850438, 2020). "As a follow-up to our previous investigation, in which we discovered a differential expression profile of ZEB1 in various endometriotic lesions, we evaluated the expression of E-CADHERIN and miR-200b in various kinds of endometriosis." (PMID 40002936, 2025). "In summary, EMT-related transcription factors such as Snail, Slug, Twist, ZEB1, and FOXC2 are central to the regulation of epithelial plasticity and invasive behavior in endometriosis." (PMID 40806587, 2025). "Considering the relationship between the transcription factor ZEB1 in EMT and its expression levels in women with endometriosis, we decided to study its expression in granulosa cells derived from infertile women undergoing IVF treatment." (PMID 37685721, 2023). "It is shown that miR-200b-3p contributes to the feedback regulation of EMT by downregulating ZEB1 and ZEB2 in endometriosis." (PMID 36289820, 2022). "Based on their findings, miR-200b-3p was linked to transcription factors such as DNA methyltransferase 1 (DNMT1), enhancer of zeste homolog 2 (EZH2), Hepatocyte nuclear factor-1-beta (HNF1B), MYB, JUN, ZEB1, and ZEB2 during endometriosis pathogenesis." (PMID 36289820, 2022). "Several studies have investigated the biological role of miR-200 family members in endometriosis and shown that these family members prevent EMT by suppressing ZEB1 and ZEB2 expression." (PMID 36289820, 2022). "In another example of direct transcriptional regulation by an lncRNA in endometriosis, AFAP1-AS1 directly activates expression of EMT-related transcription factor ZEB1 in vitro." (PMID 34768856, 2021). "Then, DNMT1, EZH2, HNF1B, JUN, MYB, ZEB1, and ZEB2 were found as TFs related to endometriosis by interacting with target genes of miR-200b-3p." (PMID 32802844, 2020). "Other studies showed that miR-200b-3p downregulates ZEB1 and ZEB2 in endometriosis patients and participates in the feedback regulation of EMT, which more easily promotes cell invasion and metastasis." (PMID 32802844, 2020). "Recently, EMT was described in endometriosis, and many EMT-specific pathways like Twist, Snail, Slug, Zinc finger E-box-binding homeobox 1/2 (ZEB1/2), E/N-cadherin, keratins, and claudins are involved." (PMID 32570986, 2020). "miR-200b-3p was associated with the transcription factors DNMT1, EZH2, HNF1B, JUN, MYB, ZEB1, and ZEB2 during the pathogenesis of endometriosis." (PMID 32802844, 2020). "We identified miR-200c as an EMT-suppressive miRNA in endometriosis that acts, at least in part, by downregulating the RNA level of MALAT1, which in turn functions as a ceRNA to upregulate ZEB1 and ZEB2 by sequestering miR-200c." (PMID 29116025, 2017). "Combining the findings from our past and present studies, we discovered that ZEB1 and miR-200b had comparable expression patterns in the eutopic endometrium of women with and without deep infiltrative endometriosis when compared to normal endometrium." (PMID 40002936, 2025). "The presence of Snail1 has been shown to increase the levels of Zinc finger E-box-binding homeobox 1 (ZEB1) protein during EMT, and the expression of ZEB1 may serve as a potential indicator of invasive endometriosis." (PMID 40289074, 2025). "However, the expression of mesenchymal genes (ZEB1) and EMT suppressor genes (miR-200b) differs across the two endometriosis groups." (PMID 40002936, 2025). "No ZEB1 staining was observed in luminal nor glandular epithelial cells of eutopic normal endometrial tissue collected from endometriosis patients." (PMID 36289723, 2022).
endometriosis (continued). "The aim of this study was to compare levels of ZEB1 and ZEB2 in the peritoneal fluid and plasma between patients with and without endometriosis in order to assess their utility in the diagnostic process." (PMID 36289723, 2022). "In addition, the inclusion of markers previously identified in the peripheral blood of endometriosis patients—such as SNAIL1, SNAIL2, TWIST1, and ZEB1 —could improve our understanding of the systemic aspects of the disease." (PMID 39857742, 2025). "ZEB1 has been previously shown to be involved in 17β-estradiol-induced EMT in endometriosis, indicating a possible mechanism by which AFAP1-AS1 could affect endometriosis." (PMID 34768856, 2021). "Both ZEB1 and ZEB2 do not seem to have a significant value in the initial diagnosis of endometriosis as a single marker." (PMID 36289723, 2022).
nasopharyngeal carcinoma (18 papers, 2013 to 2025). A carcinoma arising from the nasopharyngeal epithelium. "Furthermore, the axis of NEAT1/miR-204-5p/ZEB1 was confirmed in nasopharyngeal carcinoma." (PMID 29285225, 2017). "ZEB1, a transcription factor stabilized by ATM-mediated phosphorylation, suppresses the expression of miR-205-5p in nasopharyngeal carcinoma (NPC)." (PMID 41425255, 2025). "LncRNAs like MALAT1 and NEAT1 contribute to radioresistance, with MALAT1 modulating resistance in nasopharyngeal cancer via miR-1 inactivation and NEAT1 promoting resistance through the miR-204/ZEB1 axis." (PMID 40150019, 2025). "In nasopharyngeal cancer, lncRNA MINCR upregulated radioresistance via miR-223/ZEB1, and ZEB1 (zinc finger E-box binding homeobox 1) drives the induction of EMT by activating stem cell characteristics, immune evasion, and epigenetic reprogramming." (PMID 35600868, 2022). "Aside from its anti-fibrosis effect, miR-204 was found to suppress ZEB1 to regulate EMT phenotype and radioresistance of nasopharyngeal carcinoma cells." (PMID 34442351, 2021). "It was noted that interactions of miR-203 with ZEB1 and ZEB2 suppressed metastasis and EMT in multiple cancers and, in addition, antimetastatic miR-203, inhibiting ZEB2, reduced tumor stemness and chemotherapy resistance, for example, in nasopharyngeal carcinoma." (PMID 35163224, 2022).
renal fibrosis (18 papers, 2013 to 2023). A final common manifestation of a wide variety of chronic kidney diseases characterized by glomerulosclerosis and tubulointerstitial fibrosis. "Several studies have also demonstrated the importance of the ZEB1/2 signaling pathway in renal fibrosis." (PMID 37391399, 2023). "Of note, tubular epithelial-targeted deletion of Snail60 or Twist61, both belonging to the same family of transcription factors as Zeb1, has been shown to dampen renal fibrosis and improve renal fibrosis in mice." (PMID 37121967, 2023). "Zeb1 knockdown retarded the fibroblast–myofibroblast transition (FMyT) in vitro and dampened renal fibrosis in mice." (PMID 37121967, 2023). "Efficient knockdown was further verified by immunofluorescence staining, which showed that fewer α-SMA+/ZEB1+ cells were detected in the shZeb1 mice than in the shC mice.The mice were then subjected to the UUO procedure to induce renal fibrosis." (PMID 37121967, 2023). "Zinc finger E box binding homeobox 1 (ZEB1) is a transcription factor located downstream of the TGF-β1 signaling pathway that regulates renal fibrosis." (PMID 34684716, 2021). "Next, in the early recovery state, exo-miRs (miR-9a, miR-141, miR-200a, miR-200c, miR-429), which share Zeb1/2 as a common target mRNA, were upregulated together, indicating that they reflect TGF-β-associated renal fibrosis." (PMID 30886169, 2019). "Targeting of the zinc finger E-box binding homeobox 1/2 (ZEB1/2) by miR-192 has been shown to result in renal fibrosis by activation of the TGF-β signaling pathway." (PMID 30287505, 2018). "The miRNA-mediated inhibition of E-Box repressors (e.g., Zeb1) of upstream flanking region of fibrotic genes (such as Fn1 and Collagens) under chronic Tgfβ signaling has been demonstrated to drive renal fibrosis." (PMID 23326503, 2013). "Similar observations were made in a second model, of renal ischemia‒reperfusion injury, suggesting that Zeb1 depletion in myofibroblasts could indeed ameliorate renal fibrosis." (PMID 37121967, 2023). "Next, the role of Zeb1 in fibroblast–myofibroblast transition and renal fibrosis was determined." (PMID 37121967, 2023). "During renal fibrosis linked with ER stress, TGF-β acts as a major regulator in renal tubular epithelial cells through the PI3K/Akt, Notch signaling, and Wnt/β catenin pathways via transcriptional factors such as Zeb1, Snail, TWIST1." (PMID 34645789, 2021). "Inhibition of miR-192 increased ZEB1 and decreased collagen, inhibiting renal fibrosis." (PMID 24400868, 2014). "In terms of biological significance, in vitro and in vivo studies had shown downregulation of miR-29 in conditions of renal fibrosis and both miR-29 and miR-200 respectively targeted TGF-β1-induced production of collagens I and III, ZEB1/2 and fibronectin." (PMID 36712680, 2022). "For instance, studies have demonstrated that TGF-β/Smad3 promotes renal fibrosis by inducing the expression of miR-21, miR-433, and miR-192, which in turn suppressed PTEN, Smad7, ZEB1/2, and AZIN1, respectively." (PMID 32587662, 2020). "So it was reported that TGF-β1 inhibit the expression of miR-192, and miR-192 targeted Zeb1/2 to activate TGF-β1 signaling pathway and accentuated renal fibrosis in DN." (PMID 26881255, 2016). "The zinc finger E-box binding homeobox-1 (Zeb1) and Zeb2 are two transcription factors located downstream of TGF-β1 signaling pathway which can repress E-cadherin and regulate renal fibrosis." (PMID 26881255, 2016). "For example, miR-192 targeted zinc finger E-box binding homeobox 1/2 (ZEB1/2) to activate TGF-β signaling pathway, leading to renal fibrosis proteinuria." (PMID 25258717, 2014). "Using a novel transgenic mouse strain in which MRTF-A was deleted from myofibroblasts, these investigators found that MRTF-A might rely on a transcriptional cascade consisting of ZEB1 and IRF9 to drive renal fibrosis." (PMID 37121967, 2023).